CRP (C-reactive protein)
Diseases named in the same sentence as CRP in open-access papers (continued):
Sharing a sentence is not in itself a finding about the gene and the disease.
periodontitis (continued). "Moreover, during periodontitis, it has been hypothesized that MMP-9, together with CRP, may negatively upregulate nitric oxide (NO), which in turn may adversely affect the endothelium and arterial vascular tone and finally lead to endothelial dysfunction and augmented CVD risk." (PMID 33810003, 2021). "Patients with periodontitis showed significantly higher concentrations of total cholesterol, LDL, VLDL, triglycerides, CRP, and WBC than those without periodontitis, and WBC values were associated with the grade of periodontitis." (PMID 40572711, 2025). "Consistent with previous findings in the literature, the patients with periodontitis were determined to have higher levels of DNI, CRP, neutrophils, and WBC, compared to the individuals without periodontitis." (PMID 38195732, 2024). "Adiponectin levels were significantly lower in patients with periodontitis with and without AMI compared to controls, while CRP and MIP-1α were significantly higher in patients with periodontitis with and without AMI compared to controls." (PMID 38433948, 2024). "On the other hand, significant reductions in CRP and WBC count, along with improvements in periodontitis-related parameters, were reported one month after nonsurgical periodontal treatment in patients with both periodontitis and CVD." (PMID 38667035, 2024). "They observed an upregulation of mRNA levels for C-reactive protein (CRP) and interleukin 6 (IL-6) in adipose tissue in obese but not lean mice with periodontitis." (PMID 37237407, 2023). "Additional variables that were explored included CRP levels with median values in no periodontitis patients of 6 mg/L (IQR: 4–10 mg/L), while in periodontitis patients 5 mg/L (IQR: 3–10 mg/L)." (PMID 36282792, 2023). "NSPT, despite the benefits in periodontal clinical parameters, reduced the plasma level of CRP but not the BP in patients with combined RAH and periodontitis." (PMID 37445313, 2023). "These inflammation-related mechanisms are supported by clinical studies showing significant reductions in HbA1c and CRP following periodontal therapy in T2DM patients, and in cross-sectional comparisons demonstrating higher HbA1c in diabetic individuals with periodontitis compared to those without." (PMID 41007869, 2025). "However, data yielded by human studies are presently inconsistent, as the circulating levels of CRP, TNF-α, and IL-6 are found to be elevated in T2DM patients with periodontitis in some cases, but not in others." (PMID 39337292, 2024). "Periodontitis induced by heat-killed Pg did not further increase the total bacterial load but led to increased gene expression levels of MCP-1, TNF-α, and IL-1β in the gums of AD mice and CRP levels in the plasma." (PMID 36915108, 2023). "When we stratified the analysis by periodontal status, patients with severe periodontitis showed statistically significant higher frequency of family history of T2DM, higher HbA1c scores, more chronic DM complications, higher hs-CRP and PISA values than moderate, and no/mild periodontitis patients." (PMID 33924022, 2021). "Significant differences were observed based on the presence or absence of periodontitis for the following parameters: number of missing teeth (p < 0.001), total cholesterol (p < 0.001), LDL (p < 0.001), VLDL (p = 0.002), triglycerides (p = 0.002), CRP (p = 0.007), and WBC (p = 0.016)." (PMID 40572711, 2025). "Interestingly, in individuals with stable coronary artery disease and with chronic periodontitis, nonsurgical periodontal therapy decreased serum levels of TNF‐α, IL‐6 and CRP, which could help to reduce the inflammatory burden in these individuals." (PMID 39494478, 2024).
malnutrition (456 papers, 2009 to 2026). Inadequate nutrition resulting from poor diet, malabsorption, or abnormal nutrient distribution. "Early-onset delirium was associated with a higher total anticholinergic load and C-reactive protein levels, whereas late-onset delirium correlated with malnutrition." (PMID 41676830, 2025). "By capturing the combined effects of systemic inflammation and malnutrition, the CRP/Alb ratio emerged as an independent risk factor for mortality, with particularly strong predictive performance within the first seven days of admission." (PMID 40573094, 2025). "Malnutrition is highly prevalent in Polish dialysis patients and is linked with appetite impairment, elevated CRP, reduced albumin and poorer clinical status." (PMID 41159942, 2025). "Low albumin levels are linked to an increased risk of malnutrition, reduced OS, and elevated inflammatory markers such as interleukin-6 and C-reactive protein." (PMID 40678069, 2025). "Patients with acute exacerbation of COPD frequently experience malnutrition, while the quantitative relationship between CRP and nutritional risk remains undefined." (PMID 40630494, 2025). "A prospective study involving 2,465 patients in Switzerland revealed that elevated C-reactive protein and increased malnutrition risk were associated with low serum albumin levels." (PMID 40168268, 2025). "When CRP was added to the model as a mediator, the association between malnutrition and liver stiffness remained significant (B = 2.42, SE = 0.46, p < 0.001) but was attenuated, suggesting partial mediation." (PMID 41463388, 2025). "In the current study, the median CRP levels in patients at high risk of malnutrition according to the GNRI were significantly higher than in other groups." (PMID 40094974, 2025). "Key biochemical markers—such as low serum albumin, prealbumin, hemoglobin, total cholesterol, and vitamin D levels, as well as elevated C-reactive protein—are critical indicators of malnutrition risk." (PMID 40704314, 2025). "In our study, we demonstrated that only CRP, with weak accuracy, predicted the risk of malnutrition." (PMID 41515189, 2025). "The vertical gap between regression lines at a given CRP value reflects the direct effect of malnutrition (c′), whereas the total effect (c) represents the association without accounting for CRP." (PMID 41463388, 2025). "This nutritional deficiency impairs immune responses and increases systemic inflammation, as evidenced by elevated levels of inflammatory markers such as CRP and NLR." (PMID 40507116, 2025). "In conclusion, our study highlights that key clinical indicators such as low BMI, poor clinical scores (SKS ≤ 70), impaired lung function, systemic inflammation (elevated CRP), and nutritional deficiencies were significantly associated with reduced BMD." (PMID 40671433, 2025). "Malnutrition associated with inflammation, identified by a C-reactive protein (CRP) level > 5 mg/L, is recognized as a syndrome linked to an underlying disease, characterized by muscle mass loss with or without fat mass loss." (PMID 39030397, 2024). "In this systematic review and meta‐analysis, we therefore aimed to explore the association of malnutrition compared with normal nutrition in patients with HF, on plasma natriuretic peptide and CRP levels." (PMID 38850122, 2024). "In this systematic review and meta‐analysis, normal nutrition scores based on CONUT and GNRI in patients with HF were associated with lower levels of BNP, NT‐proBNP and CRP levels compared with patients with malnutrition." (PMID 38850122, 2024). "Average performance of the trained models classifying malnutrition leaving out GLIM diagnosis criteria (total weight loss, BMI, FFMI, CRP, reduced food intake, chronic disease/inflammation, malnutrition risk; n = 127)." (PMID 39726873, 2024). "Elevated levels of CRP, for instance, are associated with acute inflammation and can signal underlying infections or chronic diseases that often accompany malnutrition." (PMID 39125381, 2024).
malnutrition (continued). "In the secondary analysis of the EFFORT trial, nutritional intervention in hospitalized adults at risk of malnutrition reduced mortality only in the cohorts with low to medium CRP levels (<100 mg/L) at baseline." (PMID 39125374, 2024). "The mean CRP concentration upon admittance was 34.106 mg/dL in patients with normal nutritional status, 61.343 mg/dL in patients at risk of malnutrition, and 30.866 mg/dL in malnourished ones." (PMID 38396693, 2024). "The mean CRP concentration at the end of hospitalization was 24.519 mg/dL in patients with normal nutritional status, 18.800 mg/dL in patients at risk of malnutrition, and 7.757 mg/dL in malnourished people." (PMID 38396693, 2024). "In a 2011 study focused on protein-energy wasting and inflammation, malnutrition was associated with all-cause mortality and CV events, while CRP levels were higher in hyporesponders and predicted all-cause mortality and CV events." (PMID 36767017, 2023). "In both groups, malnutrition and overweight were significantly associated with higher CRP and IL-6 values (both, p < 0.05)." (PMID 36904249, 2023). "The role of inflammation as a risk factor for malnutrition in HD has been recognized in previous trials, and C-reactive protein (CRP) levels have been correlated with the inhibition of albumin synthesis in this particular population." (PMID 37512123, 2023). "For blood biochemistry factors, uric acid, glucose, HbA1c, and CRP were higher in participants who have a low risk of malnutrition." (PMID 37127636, 2023). "Inflammation, manifested by an increase in C-reactive protein (CRP) and proinflammatory cytokine levels in the serum, is an important cause of malnutrition." (PMID 36904235, 2023). "In both groups, malnutrition and being overweight were significantly associated with higher CRP and IL-6 values (Student’s t-test, both p < 0.05)." (PMID 37887395, 2023). "A low Hb level has been linked to malnutrition, weight loss, and cancer cachexia, and a high CRP level reflects systemic inflammation." (PMID 37959327, 2023). "Patients with malnutrition determined by any of the three malnutrition scores were older and were more likely to be female with lower BMI, higher CRP level, and higher GRACE risk scores than those with normal nutritional status." (PMID 37521420, 2023). "Patients classified as malnourished exhibited a significantly elevated median CRP value (3.9 ± 5.9 mg/dL) in contrast to those at risk of malnutrition (2.9 ± 5.4 mg/dL) or having a normal nutritional status (0.8 ± 2.3 mg/dL, p < 0.001)." (PMID 37513497, 2023). "Half of the patients were at high risk of malnutrition and the mean levels of basal CRP, protein, and hematocrit were abnormal." (PMID 36078901, 2022). "the role of inflammation as a risk factor for malnutrition has been more and more recognized, C-reactive protein is one of the most frequently utilized biochemical indicators to examine inflammation." (PMID 36138351, 2022). "The most important finding in our study was the patients with diabetics with high hs-CRP level and malnutrition had a significantly increased risk of all-cause mortality." (PMID 35719150, 2022). "The diagnostic parameters of severe malnutrition diagnosis were calculated for albumin (cutoff point—3.3 g/L) and CRP (cutoff point—32.62 mg/L)." (PMID 35276861, 2022). "The high hs-CRP level or malnutrition were associated with increased risk of all-cause mortality in patients with DM." (PMID 35719150, 2022). "On the other hand, malnutrition is only associated with increased risk for poor prognosis in patients with diabetics with high hs-CRP level." (PMID 35719150, 2022). "sRAGE maintained its strength of association with overt malnutrition even after CRP, Sex and patients’ age were inserted into the model (OR 2.2; 95% CI 1.1–3.4; p = 0.035)." (PMID 35883745, 2022).
malnutrition (continued). "Through linear regression, HbA1c was positively associated with age, waist circumference, hemoglobin levels, and C-reactive protein and was negatively associated with malnutrition–inflammation." (PMID 36009406, 2022). "Higher GLR and mGPS mean higher FBG and CRP levels, and lower lymphocyte count and albumin levels, which are associated with high inflammatory status, malnutrition and immune insufficiency." (PMID 35619963, 2022). "The GPS includes the value of albumin and CRP, which are associated with inflammation and malnutrition." (PMID 36540477, 2022). "Higher CRP values correlate with an increased risk of malnutrition in ours and other studies and is increased in patients with severe malnutrition." (PMID 34898583, 2021). "In the prior report, hs-CRP level has been linked to malnutrition, inflammation, and atherosclerosis syndrome and is considered to be a risk factor for morbidity and mortality in patients with CKD31." (PMID 33479451, 2021). "Findings from this study reveal that frailty can be predicted by increasing age, low household income, being at risk of malnutrition, as well as having a low skeletal muscle mass and high serum CRP level." (PMID 32916809, 2020). "Chronic inflammatory response is associated with progressive malnutrition in cancer patients, and the Glasgow prognostic score composed of albumin and CRP based on inflammatory response is crucial for the prognosis of various tumours." (PMID 33299415, 2020). "The ALB levels < 32 g/L and CRP levels > 5 mg/L form part of the diagnostic criteria for malnutrition and cachexia." (PMID 33178828, 2020). "In patients not supplementing vitamin D and those with low vitamin D concentrations, the seasonal variation of vitamin D was significantly associated with a seasonal variation of CRP and the indices reflecting the degree of inflammation and malnutrition." (PMID 32188088, 2020). "Nonetheless, many indicators of malnutrition risk (e.g., leucocyte count, serum albumin, C reactive protein (CRP), body mass, comorbidity index, food intake) have also been shown to correlate with clinical outcomes." (PMID 33379274, 2020). "Some cohort studies showed that beyond the traditional risk factors, such as age, DM, CRP, malnutrition, or Framingham risk scores, PC levels and severity of vascular calcification led to higher CV events and mortality in CKD and HD patients." (PMID 31877718, 2019). "In this regard, we demonstrated that high mNUTRIC scores were associated with high levels of CRP and higher rates of mortality, supporting the concept that an inflammation state contributes to malnutrition and a poor prognosis." (PMID 31505759, 2019). "Biomarkers for malnutrition (albumin and transthyretin) and inflammation (CRP and α1-acid glycoprotein) were significantly associated with mortality in older men." (PMID 30249038, 2018). "TIBC was superior to albumin and CRP as a malnutrition-inflammation associated serum biomarker and predictor of physical function in this low-comorbidity patient sample." (PMID 26982967, 2016). "Malnutrition and CRP concentrations on admission were statistically associated with the final model outcome." (PMID 24886623, 2014). "In contrast, serum levels of CRP are well recognized as reflection on the generation of proinflammatory cytokines in vivo, which cause malnutrition and cardiovascular diseases via several canonical pathways and result in poor prognosis." (PMID 25587447, 2014). "When adjusting for time-dependent alterations of CRP and albumin concentrations as surrogates of inflammation and malnutrition, we confirmed the independent association between lower mortality and iron supplementation." (PMID 25462819, 2014). "CRP values on admission and malnutrition were significantly associated with low plasma selenium for both evaluation time points." (PMID 24886623, 2014). "In this context, malnutrition somewhat reduced the importance of CRP concentrations on low plasma selenium risk." (PMID 24886623, 2014).
malnutrition (continued). "We did not observe a strong linear association between HbA1c values and parameters of malnutrition such as albumin (r = 0.033, p = 0.14), phosphorus (r = 0.04, p = 0.025) or CRP (r = −0.002, p = 0.40)." (PMID 21625600, 2011). "Meanwhile, MIRT adds value by incorporating inflammatory biomarkers such as C-reactive protein (CRP), with a sensitivity of 84% in detecting malnutrition and a demonstrated association with adverse clinical outcomes, including hospitalisation and need for surgery." (PMID 41538674, 2026). "Increased C-reactive protein alone indicated higher odds for malnutrition risk at baseline." (PMID 41514593, 2025). "Routinely measured parameters, such as C-reactive protein, could serve as an early indicator of increased malnutrition risk and should be interpreted in conjunction with symptom-based nutritional screening tools in routine clinical practice." (PMID 41514593, 2025). "Malnutrition can have multiple causes, and chronic low-grade inflammation, as reflected by elevated CRP, may worsen nutritional status." (PMID 40566551, 2025). "Second, the retrospective observational design precludes causal determination – whether elevated CRP directly induces nutritional risk, malnutrition exacerbates inflammation, or both share common underlying factors remains unclear." (PMID 40630494, 2025). "The slopes reflect the association between CRP and liver stiffness within each malnutrition group." (PMID 41463388, 2025). "Combining prealbumin with inflammatory markers such as CRP or interleukin-6 (IL-6) could improve its diagnostic accuracy by helping to differentiate malnutrition from inflammation-induced hypo-prealbuminemia." (PMID 41036189, 2025). "Therefore, C-reactive protein levels can only serve as an auxiliary marker in assessing nutritional status, particularly in identifying malnutrition caused by inflammation." (PMID 40094974, 2025). "Elevated levels of IL-6 and CRP significantly increase the risk of muscle loss in terms of muscle mass and strength, leading to imbalances in muscle tissue synthesis metabolism, increased protein breakdown and malnutrition." (PMID 38760722, 2024). "CRP >10 mg/L emerged as a risk factor for malnutrition in diabetic patients." (PMID 39364802, 2024). "As a result, higher CRP levels, and hence immunological activation, are associated with lower serum albumin levels: a clear sign of defective immunity, exacerbated inflammation, and malnutrition." (PMID 38975012, 2024). "Additionally, high CRP was also significantly associated with poor outcomes, including malnutrition, a high inflammatory state, advanced tumor stage, and poorer performance status." (PMID 38555313, 2024). "The level of tissue destruction negatively impacted the nutritional status parameters, leading to lower values in NRI and biochemistry, as well as higher levels of acute-phase proteins (CRP), indicating the risk of malnutrition and the presence of inflammation." (PMID 39797126, 2024). "A CRP level of ≥3.0 mg/dL is associated with reduced food intake during last 3 months in two thirds of hospitalized geriatric patients and therefore indicative for a high risk of malnutrition." (PMID 37513497, 2023). "The fifth score defines patients at risk of protein malnutrition with acute inflammation (PMA) based on low ALB and high CRP and, similarly, there is the sixth score that helps identify patients at risk of malnutrition based on elevated markers of acute/chronic inflammation and low proteins (PMAC)." (PMID 38024369, 2023). "Moreover, along with its role in inflammation and cancer prognosis, elevated serum C-reactive protein values have been associated with the risk of malnutrition and neoplastic cachexia." (PMID 38004052, 2023). "High levels of inflammatory cytokines, such as tumor necrosis factor α (TNF-α), interleukin (IL) 1β, IL-6, and CRP, together with loss of muscle mass, could account for malnutrition in affected patients." (PMID 37630691, 2023).